CCNE2 (cyclin E2)
Diseases named in the same sentence as CCNE2 in open-access papers (continued):
Sharing a sentence is not in itself a finding about the gene and the disease.
breast carcinoma (continued). "LUT may augment the impact of anticancer drugs to control breast cancer by reducing drug resistance (tamoxifen by inhibiting cyclin E2 expression), promoting apoptosis (by blocking STAT3), and inhibiting breast cancer cell growth." (PMID 34452179, 2021). "Our analysis of TCGA public datasets revealed that CCNE2 amplification and mRNA are associated with poor prognosis in non-genome doubled breast cancers." (PMID 32823571, 2020). "However, we made the novel observation that CCNE2 amplification was also significantly enhanced in genome doubled breast cancers." (PMID 32823571, 2020). "Despite these limitations, we propose that CCNE2 overexpression may represent a potential biomarker of acquired trastuzumab resistance in patients with HER2+ breast cancer." (PMID 28120942, 2017). "Furthermore, we demonstrate that E2F8 can promote entry into the G1/S phase of the cell cycle via transcriptionally upregulating cyclin E1 and cyclin E2 expression, thus contributing to cell proliferation and tumorigenicity in human breast cancer." (PMID 26992224, 2016). "Cyclin E2 (CCNE2) is involved in the G1/S portion of the cell cycle and the over expression of CCNE2 could lead to resistance in prostate and breast cancer cells." (PMID 27487134, 2016). "Therefore, our study extends the current understanding of the alternative roles of cyclins in cell migration, identifying CCNE2 as a novel mediator of the migration of breast cancer cells and suggesting a wider role of cyclins in regulating the Hippo pathway." (PMID 26265440, 2015). "The strong association between cyclin E2 and NPAT may be due to the relatively high levels of cyclin E2 observed in breast cancer cell lines." (PMID 25741376, 2015). "This could explain the unique correlations of high cyclin E2 expression with poor outcome and genomic instability in breast cancer." (PMID 25741376, 2015). "A growing body of evidence indicates that CCNE2 is involved in breast cancer cell migration." (PMID 26265440, 2015). "To address this issue, we explored whether alterations in CCNE2 expression correlate with RNA levels and protein phosphorylation levels by analyzing a cohort of 408 breast cancer patient samples via RNA-seq and phospho-proteomics approaches." (PMID 26265440, 2015). "Several results strongly support a specific role for CCNE2 in breast cancer." (PMID 26265440, 2015). "Increased cyclin E2, but not cyclin E1, expression is associated with high expression of replication-dependent histones in breast cancers." (PMID 25741376, 2015). "Interestingly, it has been reported that cyclin E2 can be an independent and better prognostic marker for some breast cancer subtypes (including luminal A and HER2 positive) when compared with cyclin E1." (PMID 25596745, 2015). "Interestingly, in analysis of TCGA data we did observe cyclin E2 amplification in ~10% of HER2 breast cancer cases." (PMID 25221644, 2014). "Furthermore, identified six genes (TSPYL5, CD55, CCNE2, DCK, BBC3, and MUC1) susceptible to breast cancer were verified through the literature mining, GO analysis, and pathway functional enrichment analysis." (PMID 24073403, 2013). "CCNE2 has also been conformed to qualify as independent prognostic markers for lymph node-negative breast tumor patients and reported to have a predictive value in ER positive cases among breast cancer patients." (PMID 24073403, 2013). "Finally, we validated the functionality of three small molecules from the phenothiazine family of anti-psychotic drugs to down-regulate cyclin E2 expression and inhibit proliferation of tamoxifen resistant breast cancer cells." (PMID 21789246, 2011).
breast carcinoma (continued). "In addition, evidence in hormone receptor positive (HR+) breast cancers suggest potential roles for upstream receptor overexpression (FGFR2) and de novo mutations in RAS, AKT1, AURKA, CCNE2, and/or ERBB2 in the activation of ERK following acquired CDK4i/6i resistance." (PMID 38066089, 2024). "cCNE2 may be a candidate gene for estrogen-progestin-induced breast cancer." (PMID 38589898, 2024). "Interestingly, individual breast cancer cells that lack A3B are often positive for Cyclin E2." (PMID 37190094, 2023). "In conclusion, the current study showed that CCNE2, CDCA5, RAD51, TCF19, KNTC1, MCM10, and NEIL3 might contribute to EPT-related tumorigenesis in breast cancer, with CCNE2 might be a sensitive risk indicator of breast cancer risk in women using MHT." (PMID 36233194, 2022). "Analysis of the transcriptome profiles of breast cancers from TCGA showed that high cyclin E2 expression is associated with high levels of replication-dependent histones, which could explain the correlations of high cyclin E2 expression with poor outcome and genomic instability in breast cancer." (PMID 29212286, 2017). "Finally, we examined whether E2F8-mediated cyclin E1 and cyclin E2 activation in breast cancer cells was clinically relevant." (PMID 26992224, 2016). "In addition, cyclin E2 amplification has been liked to breast cancer therapeutic resistance." (PMID 25596745, 2015). "Next, we examined whether silencing of CCNE2 affects breast cancer cell proliferation." (PMID 26265440, 2015). "Thus, we hypothesized that HMGA1 and CCNE2 participate in breast cancer cell migration via YAP by interfering with YAP phosphorylation at Ser127 and promoting its nuclear localization." (PMID 26265440, 2015). "When CDK4/6 is inhibited in breast cancer cells with low CCNE1, early adaptation occurs (up to 72 h), resulting in CDK2 activation and increased cyclin E2 (CCNE2) expression, eventually leading to S phase entry." (PMID 40075623, 2025). "HBV infection lead to increased expression levels of several key genes in breast cancer cell lines, including CDK2, PCNA, CCNE2, CXCL8, E2F1, and CASP3." (PMID 40697521, 2025). "Of these, CCNE2 and PCNA have been identified as key targets of KCNQ1OT1 regulators for promoting cell proliferation in breast cancer and glioma." (PMID 38361755, 2024). "We found that eight cyclins (CCNA2, CCNB1, CCNB2, CCND2, CCNE1, CCNE2, CCNF, CCNO) were differentially expressed between breast cancer and normal tissue samples, with the cut-off criterion of log2(fold change) >1, p < 0.05." (PMID 33791304, 2021). "Some important breast cancer and tumor oncogenes, such as PARI, CCNE2 and RAD54B, were detected to have positive correlations with epithelial tissue proportion in our study." (PMID 33371906, 2020). "Finally, cyclin E2 amplification is highly prevalent (~16%) in breast cancers, indicating that pathways downstream of cyclin E2, including rereplication events, may affect the genesis of a significant proportion of breast cancers." (PMID 32823571, 2020). "Thus, cyclin E2 may be a component of E2F-driven genome doubling in breast cancer." (PMID 32823571, 2020). "Thus, the molecular mechanism of trastuzumab action in BT474 cell line may be regulated by miR-26a and miR-30b and CCNE2 overexpression might play an important role in acquired trastuzumab resistance in HER2+ breast cancer given that resistance was diminished when CCNE2 was silenced." (PMID 28120942, 2017).
breast carcinoma (continued). "Thus, it would be of great interest and importance to investigate whether E2F8 upregulates cyclin E1, and cyclin E2 expression induce proliferation and tumorigenesis in breast cancer via Rb-E2F pathway which is critical in regulating in initiation of DNA replication." (PMID 26992224, 2016). "In summary, our study has revealed that E2F8 upregulation plays an important role in breast cancer progression and E2F8 is a critical cell cycle promoter by directly upregulating CCNE1, and CCNE2." (PMID 26992224, 2016). "Here, we show that cyclin E2 (CCNE2) acts downstream of HMGA1 to regulate the motility and invasiveness of basal-like breast cancer cells by promoting the nuclear localization and activity of YAP, the downstream mediator of the Hippo pathway." (PMID 26265440, 2015). "We found by immunofluorescence that cyclin E2 co-localised with the major HLB protein, NPAT, in T-47D and MCF-7 breast cancer cells, but NPAT rarely co-localised with cyclin E1." (PMID 25741376, 2015). "Intriguingly, we found a clinically relevant relationship between HMGA1 and CCNE2 expression and the YAP/TAZ signature in breast cancer patients." (PMID 26265440, 2015). "Whereas, miR-30b is capable of reducing cell growth in breast cancer and prevent EMT in liver cancer with interaction with cyclin E2 (CCNE2) and Snail1, respectively." (PMID 25799050, 2015). "Based on the analysis of a breast cancer meta-dataset, we detected a strong correlation between the HMGA1 and CCNE2 expression levels (linear regression model, P < 10−15)." (PMID 26265440, 2015). "Then, we stratified breast cancer samples according to their relative expression levels of HMGA1 and CCNE2, obtaining a significant difference in patient distribution (chi-square, P < 10−15)." (PMID 26265440, 2015). "miR-26a was reported to directly mediate the cyclin E2 and cyclin D2 functions in HCC and breast cancer." (PMID 24116110, 2013). "Using netSAM, we identified six novel genes (TSPYL5, CD55, CCNE2, DCK, BBC3, and MUC1) as cancer biomarkers for predicting survival and metastasis in patients with breast cancer." (PMID 24073403, 2013). "A panel of six genes: CCNE2, DKFZp762E1312, EMP2, MAL2, PPIC, and SLC6A8 that were over-expressed in the blood of 81% of patients with recurrent breast cancer was then chosen as gene markers for the molecular detection of CTC." (PMID 21129172, 2010). "HBV infection may lead to increased expression levels of several key genes in breast cancer cell lines, including CDK2, PCNA, CCNE2, CXCL8, E2F1, and CASP3." (PMID 40697521, 2025). "In vivo cell experiment, we confirmed that HBV infection may lead to increased expression levels of several key genes in breast cancer cell lines, including CDK2, PCNA, CCNE2, CXCL8, E2F1, and CASP3." (PMID 40697521, 2025). "Furthermore, LINC00520 increases the expression of POSTN, CCNE2, or HSP27 by targeting miR-577, thereby accelerating the progression of breast cancer, non-small cell lung cancer, or colorectal cancer." (PMID 37516879, 2023). "On the one hand, we found that knockdown of PRMT1 decreased Cyclin E2, Cyclin B1 and CDK4 expression in MCF7 and MDA-MB-231 breast cancer cells; on the other hand, we also confirmed that ectopic expression of PRMT1 increased the expression of these mentioned proteins." (PMID 34775498, 2021). "CCNE2 overexpression is frequently observed in AML, breast cancer, lung cancer and gastric cancer." (PMID 32487779, 2020). "Of the four cyclins, CCNE1 and CCNE2 mRNA occurred at significantly higher levels in whole genome doubled (GD) tumours versus non-genome doubled (NGD) tumours in breast cancers." (PMID 32823571, 2020). "We identify that cyclin E2, unlike cyclin E1, induces inappropriate genome rereplication in breast cancer cells to drive polyploidy." (PMID 32823571, 2020). "It has been demonstrated that CCNE2, targeted by miR-26a, miR-30b, might play an important role in acquired trastuzumab resistance in HER2+ breast cancer." (PMID 31777591, 2019).
breast carcinoma (continued). "Among the genes, CCNE2, which has been connected to the migratory ability of tumoral cells, has been proved to be under the transcriptional control of HMGA1, thus promoting the migratory and invasive abilities of breast cancer cells." (PMID 31311575, 2019). "Furthermore, our results reveal a potential molecular mechanism by which E2F8 promotes cell proliferation and tumorigenicity in breast cancer, via transcriptionally activating the CCNE1, and CCNE2 promoters." (PMID 26992224, 2016). "Herein, we report that E2F8 upregulates cyclin E1 and cyclin E2 expression by directly binding to these genes promoters, further supporting the notion that E2F8 promotes breast cancer proliferation and tumorigenicity by upregulating multiple cell cycle regulators." (PMID 26992224, 2016). "CCNE2 overexpression in breast cancer cells induces genomic instability but does not affect mitotic progression." (PMID 26265440, 2015). "Altogether, our data suggests that stimulation of the hERG1 channel in breast cancer cells activates ubiquitin-proteasome-dependent degradation of cyclin E2 that is independent of GSK3-β." (PMID 25596745, 2015). "Moreover, when we classified patients according to grade and molecular subtype, we found concurrently elevated expression of both CCNE2 and HMGA1 in Grade 3 breast cancer and in the more aggressive breast cancer subtypes (luminal B and basal-like)." (PMID 26265440, 2015). "Here, we show that depletion of CCNE2 strongly impairs the migration and invasion of breast cancer cells without significantly altering their proliferation." (PMID 26265440, 2015). "Next, we used basal-like breast cancer cell lines (MDA-MB-231 and MDA-MB-157) to assess whether CCNE2 expression is dependent on HMGA1 expression." (PMID 26265440, 2015). "We have shown that the RT-qPCR-based multi-marker analysis using the six genes: CCNE2, DKFZp762E1312, EMP2, MAL2, PPIC, or SLC6A8 more than doubled the number of positive patients with recurrent breast cancer compared to the analysis of hMAM or EpCAM gene expression alone." (PMID 21129172, 2010). "CCNE2 is also a component of three prognostic gene expression signatures that predict shorter metastasis-free survival or relapse-free survival of breast cancer patients, whereas CCNE1 does not feature in any of these signatures." (PMID 20180967, 2010). "A recent study indicated that high expression levels of CCNE2 would increase the combination with minichromosome maintenance protein MCM2 and MCM7 of the pre-replication complex, subsequently promoting genomic instability and cell proliferation in breast cancer." (PMID 36233194, 2022). "Moreover, KCNQ1OT1 was aberrantly highly expressed in breast cancer (BRCA) tissues and cell lines, and it could deteriorate tumor progression via regulating miR-145/CCNE2 expression." (PMID 31827399, 2019). "Indeed, RPPA data revealed an enrichment of cell cycle‐related genes including CDC25C and PLK1 in proteins downregulated by metformin, echoing a previous report showing selective translational inhibition of cell cycle regulators such as cyclin E2 and ODC1 by metformin in breast cancer cells." (PMID 30221473, 2018). "Cyclin E2 gene amplification, but not cyclin E1, has been recently defined as marker for poor prognosis in breast cancer, and appears to play a major role in proliferation and therapeutic resistance in several breast cancer cells." (PMID 25596745, 2015). "For example, breast cancers that have become resistant to anti-estrogen therapies (that inhibit cyclin D/CDK4 activity) present an amplification of cyclin E2, suggesting that the presence of cyclin E2 could be a potential mechanism of endocrine resistance." (PMID 25596745, 2015). "Moreover, a multivariate analysis of a cohort of 1131 breast cancer patients (a subset of our meta-dataset) revealed that a low expression level of CCNE2, as well as negative lymph node status, is a significant (P = 0.01) independent factor of good prognosis." (PMID 26265440, 2015).
breast carcinoma (continued). "Among these oncogenes, TSPYL5 and CCNE2 have been already known as prognostic biomarkers in breast cancer, CD55 has been suspected of playing an important role in breast cancer prognosis from literature evidence, and other three genes are newly discovered breast cancer biomarkers." (PMID 24073403, 2013). "Similarly, breast cancers high in CCNE2 had worse overall survival, and a trend towards worse overall survival if they had not undergone genome doubling, but not in those breast cancers which were genome doubled." (PMID 32823571, 2020). "Although no specific inhibitors of CCNE2 currently exist, CDK2 inhibitors have shown efficacy in suppressing the proliferation of CCNE2‐overexpressing breast cancer cells." (PMID 41562186, 2026). "We then examined the relationship between gene amplification and genome doubling in breast cancer, by comparing CCNE1, CCNE2, CCND1 and CCND2 gene amplification in non-genome doubled and genome doubled tumours." (PMID 32823571, 2020). "CCNE1 and CCNE2 are generally assumed to have highly overlapping regulation and functions, but we examined the relationship between CCNE1 and CCNE2 mRNA expression and found that they are not highly correlated in breast cancers." (PMID 32823571, 2020).
hepatocellular carcinoma (19 papers, 2018 to 2025). A malignant tumor that arises from hepatocytes. "Although the gene encoding the other subunit of CDK2, CCNE1, has been linked to poor prognosis in hepatocellular carcinoma (HCC), there is little known about the role of CCNE2 in tumor progression." (PMID 33869043, 2021). "SIRT3, a lactylation eraser, induces apoptosis in hepatocellular carcinoma by inhibiting cyclin E2 lactylation." (PMID 40994548, 2025). "In hepatocellular carcinoma, SIRT3 reduction promotes cyclin E2 lactylation, enhancing the proliferation and invasion of hepatocellular carcinoma cells." (PMID 40994548, 2025). "Lactylation of CCNE2 promotes proliferation, migration, and invasion of hepatocellular carcinoma cells and enhances resistance to chemotherapeutic agents." (PMID 41179284, 2025). "SIRT3-mediated delactylation of cyclin E2 (CCNE2) curbs hepatocellular carcinoma cell growth by inducing apoptosis." (PMID 38773972, 2024). "For example, depletion of CBX4 reduces the levels of proliferating cell nuclear antigen (PCNA) and cyclin E2/CCNE2 while increasing the level of cyclin-dependent kinase inhibitor 2A (CDKN2A/p16) to delay the G1/S transition in hepatocellular carcinoma cells." (PMID 38994031, 2024). "The underexpression of sirtuin 3 in hepatocellular carcinoma promotes the lactylation of cyclin E2, which in turn promotes tumor progression, and sirtuin 3 is a potential therapeutic target for hepatocellular carcinoma." (PMID 37675097, 2023). "Moreover, SIRT3 has nonhistone delactylase activity, removing lactylation from the K348la site of cyclin E2 (CCNE2) in hepatocellular carcinoma (HCC) cells." (PMID 40655145, 2025). "SIRT3 is underexpressed in hepatocellular carcinoma (HCC) and can delactylate lysine 348 lactylation of CCNE2 to prohibit HCC growth." (PMID 40777993, 2025). "Research shows that lactylation at lysine 348 of cyclin E2 (CCNE2 K348la) can promote the growth of hepatocellular carcinoma (HCC) cells." (PMID 40153584, 2025). "Previous research suggested that expression of CCNE1 and CCNE2 could synergistically affect the overall survival in hepatocellular carcinoma (HCC) patients and HCC progression requires the expression of any E-cyclin." (PMID 38244572, 2024). "CCNB1, CCNE2, and FOXM1 were three other genes that were differentially expressed in more than one carcinoma with survival implications, specifically in kidney clear cell and liver carcinoma." (PMID 37345032, 2023). "MCM7 inhibition led to a decrease in the esophagus and hepatocellular carcinomas viability, colony-forming ability, and migration capacity due to reducing phosphorylation of AKT1 and mTOR proteins with decreasing CDK1, CCNE1, and CCNE2 expression levels." (PMID 37529110, 2023).